HECTD2 (HECT domain E3 ubiquitin protein ligase 2)
Diseases named in the same sentence as HECTD2 in open-access papers:
HECTD2 is named in the same sentence as 25 diseases in open-access papers, as found by Europe PMC text mining. Sharing a sentence is not in itself a finding about the gene and the disease. The quoted sentences say what the papers report.
prion disease (4 papers, 2009 to 2019). A transmissible disease that is caused by a protein that is able to induce abnormal folding of normal cellular proteins, leading to characteristic spongiform brain changes, which are associated with neuronal loss without an inflammatory response. "First identified as a prion disease susceptibility gene, HECTD2 encodes a ubiquitin E3 ligase that enhances the inflammatory response to innate stimulation." (PMID 31537638, 2019). "Hectd2 was first identified in mouse mapping studies and confirmed as a candidate in human prion disease association studies." (PMID 24833721, 2014). "Further, we report an association between HECTD2 haplotypes and susceptibility to the acquired human prion diseases, vCJD and kuru." (PMID 19214206, 2009). "We report a genotype-associated differential expression of Hectd2 mRNA in mouse brains and human lymphocytes and a significant up-regulation of transcript in mice at the terminal stage of prion disease." (PMID 19214206, 2009). "We also show that HECTD2 is associated with an increased risk of two human prion diseases—vCJD in the United Kingdom and kuru in Papua New Guinea." (PMID 19214206, 2009). "HECTD2 maps to 10q and has been implicated in susceptibility to human prion diseases which are also neurodegenerative conditions associated with accumulation of misfolded host proteins." (PMID 19754925, 2009). "Our data show that HECTD2 is linked to prion disease incubation time in mouse and is associated with sporadic and variant CJD and kuru in humans and an increase in expression is associated with a susceptibility genotype and disease pathogenesis." (PMID 19214206, 2009). "In this study, we genotyped a panel of AD patients and looked for an association with a HECTD2 SNP previously shown to be associated with prion disease." (PMID 19754925, 2009). "To test this hypothesis we carried out an association study with HECTD2 markers and samples from different human prion diseases and successfully found a significant association with two acquired forms of prion disease: vCJD and kuru." (PMID 19214206, 2009). "In this study we test whether the HECTD2 susceptibility allele seen in prion disease is also implicated in LOAD." (PMID 19754925, 2009). "We therefore analysed HECTD2 in a hypothesis-driven association study of human prion disease." (PMID 19214206, 2009). "It should also be noted that although vCJD and kuru are both acquired human prion diseases that share many characteristics they are also derived from different sources and caused by distinct prion strains therefore the mechanism of HECTD2 involvement may also be different." (PMID 19214206, 2009). "We have used a heterogeneous stock of mice to identify Hectd2, an E3 ubiquitin ligase, as a quantitative trait gene for prion disease incubation time in mice." (PMID 19214206, 2009). "This approach led to the identification of Hectd2, an E3 ubiquitin ligase, as a quantitative trait gene for prion disease incubation time." (PMID 19214206, 2009). "A potential role for Hectd2 in prion disease pathogenesis was explored by comparing the mRNA expression levels between normal mice and those at the end stage of disease following infection with Chandler/RML prions." (PMID 19214206, 2009). "Our data indicate that Hectd2 influences prion disease incubation time in mice." (PMID 19214206, 2009). "This suggests that the mode of HECTD2 action in prion disease may be independent of host and prion strain." (PMID 19214206, 2009).
kuru (3 papers, 2009 to 2010). A prion disease found exclusively among the Fore linguistic group natives of the highlands of new guinea. "Hectd2 is an example of a susceptibility gene first identified in mouse that is also associated with the human diseases vCJD and kuru." (PMID 21151910, 2010). "Recently, the E3 ligase HECTD2 has been identified as genetically associated with vCJD and kuru." (PMID 21151970, 2010).
prostate carcinoma (3 papers, 2019 to 2022). A carcinoma that arises from epithelial cells of the prostate gland. "HECTD2 was identified as a candidate driver gene in neuroblastoma or as a potential target of miR-221, which promotes androgen-independent growth of prostate cancer cell lines, thus indicating an anti-proliferative role for HECTD2 in this cancer type." (PMID 34145398, 2021). "MicroRNA-mediated down-regulation of HECTD2 expression has been proposed to drive androgen independence in prostate cancer, and more recently, HECTD2 copy number alterations were suggested as drivers in neuroblastoma patients." (PMID 31537638, 2019). "The study has also indicated that HECTD2 is a downstream target of miR-221 and miR-221 could inhibit the expression of HECTD2 to boost the development of androgen independence in prostate cancer cells." (PMID 35186224, 2022). "HECTD2 expression has also been shown to be directly regulated by miR-221 in prostate cancer cells." (PMID 34145398, 2021). "Despite its essential role in maximal NF-κB activation, HECTD2 has not been previously associated with the cell cycle and the only currently available data suggest an anti-proliferative role for HECTD2 in androgen-independent growth of the LNCaP prostate cancer cell line." (PMID 34145398, 2021).
Alzheimer disease (2 papers, 2009). A progressive, neurodegenerative disease characterized by loss of function and death of nerve cells in several areas of the brain leading to loss of cognitive function such as memory and language. "Further, HECTD2 maps to a region of human chromosome 10q previously linked with Alzheimer's disease suggesting that HECTD2 may also be a susceptibility factor for Alzheimer's disease and other neurodegenerative disorders." (PMID 19214206, 2009). "DNA from 320 individuals with Alzheimer's disease and 601 controls were genotyped for a HECTD2 intronic tagging SNP, rs12249854 (A/T)." (PMID 19754925, 2009).
melanoma (2 papers, 2022 to 2025). A malignant, usually aggressive tumor composed of atypical, neoplastic melanocytes. "Melanoma patients with high level HECTD2, the E3 ubiquitin ligase involved in ubiquitin mediated proteolysis, had worse antitumor immunity and worse outcome of ICI treatment than those with low level HECTD234." (PMID 36241866, 2022). "Similarly, antisense transcription has been reported to regulate levels of the E3 ubiquitin ligase HECTD2, which would otherwise exert a clear tumour-promoting effect in melanoma." (PMID 40336011, 2025).
acute respiratory distress syndrome (1 paper, 2020). Progressive and life-threatening pulmonary distress in the absence of an underlying pulmonary condition, usually following major trauma or surgery. "The ubiquitin E3ligase encoded by HECTD2 has been shown to have a proinflammatoryrole in the lung, and other HECTD2 variants may be protectiveagainst acute respiratory distress syndrome." (PMID 31710517, 2020).
colon cancer (1 paper, 2022). "Our findings suggest that microbiome-induced propionate inhibits the activity of HDAC to upregulate HECTD2 expression in colon cancer." (PMID 34972816, 2022). "Thus, the induction of HECTD2 expression by propionate may promote the proteasomal degradation of EHMT2; accordingly, the growth of colon cancer was suppressed by apoptosis induced by EHMT2 reduction." (PMID 34972816, 2022).
hepatocellular carcinoma (1 paper, 2025). A malignant tumor that arises from hepatocytes. "Targeting HECTD2 using PLGA‐PEG‐based nanoparticles offers novel strategies to overcome lenvatinib resistance in hepatocellular carcinoma." (PMID 39976163, 2025). "Cross‐referencing these results with the cancer genome atlas–liver hepatocellular carcinoma database, revealed that HECTD2 was among the top ten upregulated proteins in lenvatinib‐resistant HCC cells." (PMID 39976163, 2025). "HECTD2 serves as an E3 ubiquitin ligase of KEAP1 to facilitate the antioxidative response and contributes to lenvatinib resistance in hepatocellular carcinoma." (PMID 39976163, 2025).
leukemia (1 paper, 2013). A malignant (clonal) hematologic disorder, involving hematopoietic stem cells and characterized by the presence of primitive or atypical myeloid or lymphoid cells in the bone marrow and the blood. "More interestingly, we also found other genes that had never been associated with leukemias nor with other types of cancer, or had no assigned function such as the Exoc3l4, Hectd2 and AU014947." (PMID 23902727, 2013).
metastatic disease (1 paper, 2021). "Clusters characterised by high HECTD2 expression (2 and 4) were enriched for metastatic disease, where HECTD2 expression is higher." (PMID 34145398, 2021).
metastatic melanoma (1 paper, 2021). A melanoma that has spread from its primary site to another anatomic site. "We find that this expression is maintained in primary melanoma and further elevated in metastatic melanoma, supporting a link between high HECTD2 expression and melanoma progression." (PMID 34145398, 2021). "Although the loss of HECTD2 function was variable and overall neutral for cell lines derived from metastatic melanoma, a potentially negative effect on growth was observed for lines derived from primary melanoma, in proportion with HECTD2 expression." (PMID 34145398, 2021).
Sepsis (1 paper, 2022). Sepsis is defined as life-threatening organ dysfunction caused by a dysregulated host response to infection. "The expression of HECTD2 in the control group was the lowest, and the expression of HECTD2 in the miR-221 mimic group was significantly higher than that in the sepsis group." (PMID 35186224, 2022). "Compared with the control group, the expression levels of miR-221 and HECTD2 in the sepsis group were significantly increased." (PMID 35186224, 2022).
sporadic CJD (1 paper, 2009). "We tested whether genetic variation at HECTD2 was associated with a phenotype of variant and sporadic CJD." (PMID 19214206, 2009).
cancer (7 papers, 2013 to 2026). A tumor composed of atypical neoplastic, often pleomorphic cells that invade other tissues. "MiR-221 and miR-222 are two small non-coding RNAs with the same seed sequence that have been implicated in cancer and their targeting of HECTD2 could extend its involvement beyond melanoma." (PMID 34145398, 2021). "We recently examined the transcriptional activity of endogenous retroviruses in cancer and identified a novel transcript spanning the HECTD2 locus and expressed uniquely in melanoma." (PMID 34145398, 2021). "HECTD2 additionally regulates cancer cell production of immune mediators, initiating multiple immune suppressive pathways, which include the cyclooxygenase 2 (COX2) pathway." (PMID 34145398, 2021). "Identified through screening for cancer-specific endogenous retroviral transcripts, we show that the little-studied E3 ubiquitin ligase HECTD2 exerts dominant control of tumour progression in melanoma." (PMID 34145398, 2021). "Consistent with melanoma biopsies, the vast majority of human melanoma cell lines from the cancer cell line encyclopaedia (CCLE) expressed medium to high HECTD2 levels, with the exception of SK-MEL-3 and IGR-1 cells, where HECTD2 levels were very low." (PMID 34145398, 2021). "The results indicated that HECTD2 is involved in a KEGG pathway of MicroRNAs in Cancer." (PMID 35004677, 2021). "HECTD2 expression may additionally be regulated by the lncRNA ERP in human cancer, as has been suggested by studies in epithelial cells." (PMID 34145398, 2021). "This central, multifaceted role of HECTD2 in cancer cell-autonomous proliferation and in immune evasion may provide a single target for a multipronged therapy of melanoma." (PMID 34145398, 2021). "However, the function of HECTD2 in cancer in general and in melanoma in particular remains to be elucidated." (PMID 31537638, 2019). "Furthermore, propionate, as a histone deacetylase (HDAC) inhibitor, blocks histone deacetylation, leading to chromatin relaxation and the transcriptional activation of pro-apoptotic genes such as HECT domain E3 ubiquitin protein ligase 2 (HECTD2), ultimately inducing apoptosis in cancer cells." (PMID 41355959, 2026). "Using both in vitro and in vivo models, we observed a significant upregulation of HECTD2 expression in lenvatinib‐resistant HCC cell lines, patient‐derived organoids, PDX mouse models, and patient cancer tissues." (PMID 39976163, 2025). "Inspection of cancer dependency map (DepMap) data indicated that HECTD2 is not an essential gene in cell lines from multiple cancer types, including melanoma." (PMID 34145398, 2021). "In most healthy tissues and cancer types, however, HECTD2 expression is not subject to regulation by antisense transcription." (PMID 34145398, 2021).
tumor (6 papers, 2017 to 2025). "Collectively, these data confirm the direct link between HECTD2 overexpression and increased NF-κB activity, which likely underlies the effect of HECTD2 on the cell cycle and immunogenicity of tumour cells." (PMID 34145398, 2021). "Accordingly, higher HECTD2 expression is associated with weaker anti-tumour immunity and unfavourable outcome of PD-1 blockade in human melanoma and counteracts immunity against a model tumour antigen in murine melanoma." (PMID 34145398, 2021). "IHC staining of HCC organoids and the corresponding primary tumor tissues showed that lenvatinib‐resistant organoids and tumor tissues exhibited elevated expression levels of HECTD2 and NRF2, along with reduced KEAP1 expression." (PMID 39976163, 2025). "qRT‐PCR results confirmed that HECTD2 mRNA expression was significantly elevated in lenvatinib‐resistant organoids and the corresponding patient tumor samples." (PMID 39976163, 2025). "Overall, our study confirmed that 1) HECTD2 is up-regulated in RCC and aggravates RCC progression; 2) miR-320a functions as a tumor suppressor in RCC by targeting HECTD2; 3) HIF-1α induces HECTD2 upregulation by repressing miR-320a." (PMID 35004677, 2021). "The results suggested that both HIF-1α and HECTD2 were up-regulated in RCC (compared with adjacent non-tumor tissues), and they had positive relationship." (PMID 35004677, 2021). "Collectively, our results point to a critical role for HECTD2 in promoting melanoma cell-intrinsic proliferation and drug resistance and counteracting anti-tumour adaptive immunity and immunotherapy." (PMID 34145398, 2021). "We constructed a HECTD2 overexpression model in 786-O and A-498 cells to testify the influence of HECTD2 on tumor growth in vivo and found that overexpressing HECTD2 significantly heightened tumor volume and weight (p < 0.05)." (PMID 35004677, 2021). "To examine the overall effect of HECTD2 expression on melanoma growth in vivo, we employed the three transplantable murine cell lines, HCmel31, BrafV600E and B16, and monitored tumour formation and infiltration by diverse immune cell types." (PMID 34145398, 2021). "As a matter of fact, HECTD2 has been reported to exert a prominent role in tumor and is modulated by miRNA." (PMID 35004677, 2021). "Two potential tumor suppressive targets, HECT domain E3 ubiquitin protein ligase 2 (HECTD2) and RAB1A, were identified by the combination of RNA immunoprecipitation and miR-221-3p target prediction programs." (PMID 33353171, 2020). "Moreover, overexpression of HECTD2 in a mouse melanoma model diminished the effectiveness of the adaptive immune response to a model tumour antigen." (PMID 34145398, 2021). "Moreover, WB results demonstrated that overexpressing HECTD2 in 786-O and A-498 cells significantly facilitated the HECTD2 profile in the transplanted tumor tissues (p < 0.05)." (PMID 35004677, 2021). "Also, WB results uncovered that HIF-1α and HECTD2 expression levels were significantly higher in tumor tissues of RCC patients than those in corresponding surrounding non-tumor tissues." (PMID 35004677, 2021). "HECTD2 overexpression in B16 cells caused a slight delay (1–2 days) in tumour growth but did not appreciably alter the outcome of immune response to the rumours." (PMID 34145398, 2021). "However, HECTD2 knockdown suppressed RCC tumor volume and weight (vs. the HIF-1α group) (p < 0.05)." (PMID 35004677, 2021). "Overexpressing HECTD2 in PDX models enhanced resistance to lenvatinib treatment, leading to increased tumor volume and weight." (PMID 39976163, 2025). "Here, we discovered that HIF-1α and HECTD2 were enhanced in RCC, and in-vivo studies testified that overexpressing HECTD2 and HIF-1α hampered apoptosis and induced tumor growth of RCC cells." (PMID 35004677, 2021). "Additionally, immunofluorescence analysis demonstrated high HECTD2 and low KEAP1 expression in lenvatinib‐resistant tumor tissues." (PMID 39976163, 2025).
tumor (continued). "To further validate the impact of the HIF-1α/HECTD2 axis on tumor growth in vivo, we established HIF-1α overexpression and/or HECTD2 knockdown models in 786-O cells and discovered that overexpressing HIF-1α increased tumor volume and weight (vs. the vector group)." (PMID 35004677, 2021). "The combination of these findings suggested that a potential anti-tumour immune response promoted by the pro-inflammatory activity of HECTD2 was either non-functional or counteracted by a stronger immune-suppressive activity." (PMID 34145398, 2021). "Induction of the immunosuppressive ‘COX2’ module by HECTD2 offers one explanation for the negative effect on anti-tumour immunity we observed in this study." (PMID 34145398, 2021). "In this study, downregulation of HECTD2 affected androgen related transcription, and downregulation of HECTD2 and RAB1A altered the expression of many cell cycle genes and pathways, promoting tumor metastasis and leading to the development or maintenance of the CRPC phenotype." (PMID 28275218, 2017). "Similarly, HECTD2 overexpression increased the immune infiltration of otherwise immune-depleted HCmel31 tumours but did not further enhance the infiltration of more immunogenic BrafV600E and B16 tumours." (PMID 34145398, 2021). "Therefore, overexpression of HECTD2 in HCmel31 cells autonomously increased their in vivo growth and ignited immune infiltration of tumours formed, which, however, did not restrain their growth." (PMID 34145398, 2021). "To examine if elevated HECTD2 expression may correlate with a lack of effective T cell anti-tumour immunity, we analysed cohorts of melanoma patients that were treated with PD-1 blocking antibodies." (PMID 34145398, 2021). "Thus, although HECTD2 expression alone was sufficient to attract immune cells to the otherwise non-immunogenic HCmel31 tumours, it did not promote T cell-mediated tumour resistance and even negated the resistance provided by the immunogenic expression of FB29 gp70 as a tumour-specific antigen." (PMID 34145398, 2021).
infection (1 paper, 2009). The state of being infected such as from the introduction of a foreign agent such as serum, vaccine, antigenic substance or organism. "Our expression analysis in terminally sick mice suggest that HECTD2 is upregulated during the course of infection therefore we can speculate that a higher base line of expression reduces the time taken to reach a threshold level thereby reducing the incubation time." (PMID 19214206, 2009).
neurodegenerative disease (1 paper, 2009). A disorder of the central nervous system characterized by gradual and progressive loss of neural tissue and neurologic function. "Based on linkage data, association with another neurodegenerative disease and association with the ubiquitin-proteosome system, HECTD2 is a promising candidate susceptibility factor for LOAD." (PMID 19754925, 2009).
HECTD2 also shares sentences with these, for which no sentence is quoted: colorectal cancer (3 papers); neuroblastoma (2); cervical cancer (1); idiopathic pulmonary fibrosis (1); kidney injury (1); non‐small cell lung cancer (1); pneumonia (1); renal cell carcinoma (1).